CD44 (CD44 molecule (IN blood group))
Diseases named in the same sentence as CD44 in open-access papers (continued):
Sharing a sentence is not in itself a finding about the gene and the disease.
tumor (continued). "To further elucidate the respective roles of CD44-mediated transcytosis in tumor ECs and tumor cells, we also generated CD44−/− HUVEC and CT26 cells, respectively." (PMID 38177179, 2024). "We further verified the mouse tumor tissue by immunofluorescence, and found that the expressions of CD11b+CD44+PD-L1+ were significantly increased in the AA group compared with the PBS group, which were consistent with the results of mass cytometry." (PMID 38822322, 2024). "The coordinated functions of these enzymes provide varying levels and sizes of hyaluronan in the tumor microenvironment that in turn affect its interaction with CD44 and the degree and outcome of CD44 signaling in tumor and stromal cells." (PMID 38796656, 2024). "We determined the frequency of TISCs in our HS diet tumor model by flow cytometry analysis of CD44+C24- cells." (PMID 38891044, 2024). "In recent years, although few studies have investigated the c‐Src signaling pathway in cancer regulated by CD44, accumulating evidence suggests that activation of c‐Src plays a key part in tumor progression." (PMID 38783892, 2024). "CD44 is a multifunctional cell-membrane adhesion receptor that promotes tumor progression, invasion, metastasis, and epithelial-mesenchymal transition through various mechanisms including nuclear translocation." (PMID 39268460, 2024). "A study verified that alkylamine-modified HA enhances the targeting of HA to CD44 and significantly boosts the uptake efficiency of tumor cells." (PMID 38799466, 2024). "Conversely, CD44 exhibited widespread expression in the membrane and transmembrane regions of tumour cells across all sites." (PMID 38719848, 2024). "Inhibition of iRhom1 further facilitates tumor targeting and uptake through inhibition of CD44 cleavage." (PMID 38177179, 2024). "Despite the differences not being statistically significant, we can observe that the mRNA expression of stemness markers CD24 and CD44 were decreased in tumor tissues treated with NVB (P = 0.0687; P = 0.0796)." (PMID 38575587, 2024). "Immunohistochemical detection indicated that α-Hederin (40 mg/kg) treatment increased Tunel and E-cad and suppressed Ki-67 and CD44 expression in xenograft tumor tissues." (PMID 38244586, 2024). "BSCS subpopulations with the CD44+/CD24- phenotype or high ALDH activity were analyzed to verify the role of NSDHL in maintaining the BCSC population within tumor tissues." (PMID 39516821, 2024). "Tumor sphere assay conducted using cells with stably silenced (SCC15-CD44+) or overexpressed (CAL27-CD44+) METTL3 showed that METTL3 upregulation promoted CD44(+) self-renewal potential." (PMID 38355684, 2024). "Converted SIY-specific cells in the TdLN were highly enriched for CD44+CD62L− effectors (Fig. 3biii), consistent with the fact that the majority of SIY-specific cells in the tumor are also CD44+CD62L−29." (PMID 38789721, 2024). "Specifically, SPP1 released from tumor cells interacted with CD44, ITGAV, ITGA5, ITGB1, and ITGB5 on immune clusters." (PMID 39505867, 2024). "Except for CD44, which was only expressed in the C2-E.T and C7-Tumor cell clusters, all receptor and ligand genes were broadly expressed among these nine cell clusters." (PMID 38191424, 2024). "Hinokitiol led to tumor spheroids shrinkage as inhibited BC stem-like cells self-renewable capacity, suppressed tumor stemness-progression via inhibiting CD44/Nanog/SOX2/Oct4 signaling pathways." (PMID 38612715, 2024). "The addition of TCM allowed us to partially mimic the TME, where tumor-derived factors, like prostaglandins, soluble CD44 and succinate, influence the differentiation and polarization of macrophages." (PMID 38302493, 2024). "Using in vivo experiments, it has also been shown that CD44(+) cells have a more elevated tumor initiation potential than the CD44(-) ones." (PMID 38355684, 2024).
tumor (continued). "HA and CD44’s connection encourages epidermal growth factor receptor-mediated pathways, which therefore results in the growth of tumor cells, tumor cell migration, and chemotherapy resistance." (PMID 39026213, 2024). "When compared with normal group, CD56bri_CCL5 cells in tumor demonstrated an increased interaction weight with macrophage cells through the MIF-(CD74+ CD44) ligand-receptor pair." (PMID 38552055, 2024). "This sequence contains the recognition of hyaluronan (HA), an abundant component of ECM expressed by stromal and tumor cells, and the primary ligand of CD44." (PMID 38672650, 2024). "CD44 is considered as an important cell surface receptor, which is involved in cell matrix interactions and tumorigenic signaling, and regulates tumor cell phenotype, stemness and aggressiveness." (PMID 38796656, 2024). "Based on previous studies and our results, we concluded that POLE2 promoted tumor progression of OS cells by maintaining the expression of CD44." (PMID 38627379, 2024). "CS, as a natural ligand of CD44, was also included to mediate active targeting of tumor cells and tumor endothelial cells (ECs) as CD44 is overexpressed in both types of cells." (PMID 38177179, 2024). "The nanocomplex's surface was decorated with HA to enhance tumor targeting via CD44 overexpression and to mitigate toxicity, extending circulation time significantly." (PMID 39479443, 2024). "Serglycin (SRGN) secreted by tumour cells activated the CD44/c-Myc pathway to upregulate KDM5B expression, thereby promoting IL-8 production in CAFs." (PMID 38862740, 2024). "Accumulating evidence suggests that CS modifies the drug delivery of nanoparticles that target CD44 into tumor cells with low cytotoxicity." (PMID 38783892, 2024). "The nanosystem showed specific targeting toward cancer cells with high CD44 expression in CT-26 tumor-bearing mice owing to the presence of hyaluronic acid." (PMID 39479443, 2024). "CD44 interacts with several ligands, including HA, chondroitin, collagen, laminin, and fibronectin, which are responsible for their ability to promote tumor progression and increase aggressiveness." (PMID 38672650, 2024). "We identified a novel subset of macrophages that, through secretion of SPP1, bind to CD44 on tumour cells, activating the PDE3B pathway via the integrin enzyme pathway, thereby inducing chemotherapy resistance in TNBC patients." (PMID 38982317, 2024). "HMGB2 in POSTN+ fibroblasts is predicted to bind to PLD2, LRP5, MYLK, and CD44 on tumor cells, regulating downstream genes, including BIRC5, CCNA2, CCNB1, CCNB2, CDC20, and MKI67, which are related to the cell cycle." (PMID 38519500, 2024). "Although CD44 is considered as a versatile tumor-promoting cell surface receptor its contribution to TGCTs biology has not been evaluated." (PMID 38796656, 2024). "CD44 also plays a key role in regulating the properties of CSCs, including self-renewal, tumor initiation, and chemoresistance." (PMID 38542115, 2024). "The binding of CD44 to MMPs has also been reported to mediate tumor growth, stemness, as well as the aggressive behavior." (PMID 38783892, 2024). "CD44-mediated tumor targeting has been studied for decades but the underlying mechanism remains elusive, especially the respective role of CD44 in tumor ECs and tumor cells." (PMID 38177179, 2024). "The probe 89Zr-DFO-scFv-Fc-CD44 demonstrated outstanding tumor uptake, which warrants the possibility of further clinical evaluation." (PMID 38609981, 2024). "CD44 levels were correlated with tumor aggressiveness in muscle-invasive BC patients, and it was observed that the tumorigenic potential of CD44+ tumor cells in immunocompromised mice was at least 10 to 200 times greater compared to that of CD44 cells." (PMID 38607066, 2024).
tumor (continued). "The bulk RNA‐seq data from the ICC cohort at Fudan University corroborate the positive correlation between the enrichment of the SPP1+ macrophage signature and the elevated levels of both the tumor stemness signature and CD44 expression." (PMID 39716897, 2024). "Upon CD44 kd, tumor angiogenesis was increased in the paranecrotic areas, accompanied by reduced hypoxia‐inducible factor‐1α and CEACAM5 but increased E‐cadherin expression." (PMID 37849446, 2024). "To investigate the mechanisms orchestrating cancer stemness and tumour development, we analysed the transcriptional differences between differentiated (Krt20+Apoc2+Fabp2+) and stem (Lgr5+Cd44+Sox9+) cancer cells within tumours." (PMID 38658753, 2024). "EMT enhances tumour cell mobility, invasion, and metastasis, therefore upregulation of CD44 with a fibroblast stroma is expected when taking into consideration the corresponding invasion distance data." (PMID 38226014, 2024). "In breast cancer specifically, CD44+ cells have superior spheroid colony formation in serum-free medium in vitro, as well as enhanced tumor frequency when injected into severe combined immunodeficient (SCID)." (PMID 39840036, 2024). "Using the CellChat R package, intercellular communication analysis revealed that tumor-associated macrophages (TAMs) interact with other cells in the PCa TME primarily through MIF - (CD74+CXCR4) and MIF - (CD74+CD44) ligand-receptor pairs." (PMID 38663915, 2024). "MiRNAs can directly bind to CD44 to silence gene expression at the RNA level, which has been shown to regulate CSCs characteristics and tumor progression." (PMID 38783892, 2024). "A significant decrease in Pearson's correlation coefficient was observed in a dose‐dependent manner in the tumor tissue of CD24−/CD44+ xenotransplanted groups treated with low and high doses of doxorubicin as compared to the untreated groups." (PMID 38522013, 2024). "Our recent study suggested an important role of targeting of tumor ECs through CD44 in the overall tumor targeting." (PMID 38177179, 2024). "The combination of CD44 with HA has also been confirmed to regulate a spectrum of phenotypic traits in cancer cells, such as tumor progression, metastasis, and proliferation." (PMID 39339402, 2024). "CD44, a cell surface transmembrane glycoprotein, is involved in tumor cell differentiation, invasion, and metastasis." (PMID 39619442, 2024). "We found fewer CD133+CD44+ cells (17.2%) in Gtpbp2−/− CCSC-derived tumor cells in comparison to Gtpbp2+/+ CCSC-derived tumor cells (22.6%), suggesting weaker self-renewal of Gtpbp2−/− CCSCs." (PMID 38468952, 2024). "It was found that both CD44 and E-cadherin decreased with the grade of tumor, while EGFR and vimentin increased with tumor de-differentiation." (PMID 39050298, 2024). "Our findings indicate that the overall expression of FAK, HIF-1α, Ki67, and CD44 was higher in tumor nests, whereas that of ILK was higher in tumor stroma." (PMID 38727811, 2024). "This nanocarrier is effective in tumor targeting and penetration through both enhanced permeability and retention effect and CD44-mediated transcytosis in tumor endothelial cells as well as tumor cells." (PMID 38177179, 2024). "A significant relationship exists between increased CD44 expression and clinical indicators such as tumor grade and tumor cell differentiation in cancer patients." (PMID 39217459, 2024). "Previous studies have demonstrated that upregulation of ITGB1 and CD44 can promote tumor progression and invasion." (PMID 38233802, 2024). "CCND1, AKT1 and CD44 were all expressed at significantly higher levels in the tumour compartment of p16-/HPV- relative to p16+/HPV+ OPC, with CCND1 also being upregulated in the stromal compartment." (PMID 39328208, 2024). "The CD44+/CD24low/− phenotype predominantly characterizes the mesenchymal subtype, typically localized in the tumor periphery, contributing to tumor metastasis." (PMID 39000554, 2024).
tumor (continued). "Numerous studies have demonstrated the ability of HA to target CD44-overexpressing cancer cells; however, it must be remembered that the level of CD44 expression can differ by an order of magnitude depending on the tumor, as we have showed in our study." (PMID 38672482, 2024). "CD44 expression was found to positively correlate with PDL1 expression in various tumours, as well as with immune infiltration." (PMID 38539419, 2024). "CD44 is abundantly expressed on EVs derived from different tumor cells, and several reports have shown that the transfer of EV CD44 to distinct recipient cells plays a major role in promoting chemo resistance, tumor progression, and metastasis." (PMID 38542421, 2024). "This CD44-HA interaction is a central role in hematogenous tumor metastasis, shaping the metastatic potential of cancer cells." (PMID 39758992, 2024). "The research indicates that CD44 in CAFs is active in sustaining cancer stem cell populations within the tumor microenvironment." (PMID 39408826, 2024). "Currently, most studies focus on CD44 as a surface marker of CSCs to promote tumor development and induce chemotherapy resistance through self-renewal and EMT pathways." (PMID 38590654, 2024). "In the initial phase of our investigation, we examined the correlations among CD44 I and CD44 II staining outcomes in tumor tissue, which we observed to influence OS potentially with TS and LVI." (PMID 38903413, 2024). "CD44 is involved in tumor malignant progression through the promotion of tumor cell proliferation, migration, invasiveness, and stemness." (PMID 39273139, 2024). "Another protein involved in regulating the tumor microenvironment pathway is CD44, of which the expression in A549 cells treated with DDP and TSA was also downregulated (FC = −1.35)." (PMID 38893499, 2024). "In summary, anti-tumor therapy targeting CD44 holds great promise in improving and extending the survival of cancer patients." (PMID 38590654, 2024). "We also found that the presence of CD44+ALDH1+ABCG2+ tumor cells steadily increased over time (p < 0.001)." (PMID 38534924, 2024). "In this study, we detected the expression of CD44 in tumor tissues of tumor bearing mice treated with various drugs using immunohistochemistry." (PMID 39014462, 2024). "Morphological changes and increased invasion capacity of human peritoneal mesothelial cells (HPMCs) are observed upon treatment with CD44 expressing tumor cell-derived exosomes." (PMID 38796525, 2024). "BCSCs expressing CD44+/CD24– have a greater capacity for tumor development in mice, prompting us to examine their expression status by flow cytometry." (PMID 39452867, 2024). "This is supported by the fact that miR-34a which decreases CD44 expression in prostate cancer stem cells can block tumor growth and metastasis." (PMID 38903499, 2024). "Our study has shown that regulatory factor X1 (RFX1) is a tumour‐suppressive transcription factor that can downregulate the expression of CD44 and growth factors." (PMID 39636301, 2024). "Given its critical role in tumor stem cell maintenance and tumor progression, CD44 has become an attractive target for cancer therapy." (PMID 39184916, 2024). "A single CD44+ cell can proliferate into stem-like tumor spheres in vitro, and tumor spheres xenografted into nude mice can develop into tumors." (PMID 38254219, 2024). "Conversely, the bulk of the tumours was composed of cells with different degrees of differentiation, as revealed by the downregulation and upregulation of CD44 and FABP1, respectively." (PMID 38658753, 2024). "Given their involvement in multiple cellular functions, CD44 and HA are linked with regulating CSC properties such as self-renewal and tumor initiation." (PMID 38672650, 2024). "Here, we encapsulate the present understanding of the structural and functional roles of CD44 in neoplastic diseases as well as CD44‐regulated signaling pathways." (PMID 38783892, 2024).
tumor (continued). "Within the 5-year deceased cohort, there was significant enrichment (P < 0.05) of cell-to-cell contact between PD-1+ Memory Helper T cells and Tumor cells, Neutrophils, Proliferating cells, CD44+ cells, HLA-A+ cells, MDSCs, and Macrophages." (PMID 39333065, 2024). "The resulting tumor weights at necropsy were lower in the CD44 kd group (mean 0.7825 ± 0.654 g) than in the control group (mean 1.088 ± 0.384 g, P = 0.043, Wilcoxon rank sum test with continuity correction)." (PMID 37849446, 2024). "We performed immunohistochemistry in tissue sections to evaluate the expression of CD44 in tumor and stromal cells." (PMID 38796656, 2024). "CD44 regulates cell adhesion, proliferation, survival, and stemness and has been considered a tumor therapy target." (PMID 39273139, 2024). "As shown in the averaged intensity-based heatmap and in line with transcriptomic studies in PDAC, tumor cells were further reclassified into 7 different subtypes, based on the expression of Pan-Ck, Ck-7, CD44, S100A4 and CA-IX." (PMID 39575252, 2024). "Collectively, our data suggest that the TGF-β1/SMAD3 axis is critical for the regulation of the anti-tumor activities of CD44+CD8+ T cells by CRC cell-expressed ATP6V0A1." (PMID 38971819, 2024). "Upregulation of both CD44 and hyaluronan under hypoxic conditions most likely amplify the signaling events and lead to tumor progression." (PMID 38877052, 2024). "For example, AR gene suppression in PCa models (e.g., DU145 and LNCaP) increases self-renewal capacity and significantly upregulates relevant tumor stem cell markers, such as CD44, SOX2, and acetaldehyde dehydrogenase (ALDH)." (PMID 39092186, 2024). "HA also can promote tumor targeting, via either active targeting through binding to CD44 and other cell surface receptors or passive targeting through enhanced permeation retention phenomena (EPR)." (PMID 39329973, 2024). "The results showed that CD44v6 CAR ‐T cells produced anti‐tumour cytokines and effectively cleared CD44+ tumour cells." (PMID 38712978, 2024). "In contrast to the AS-mediated reduction in the efficacy of anti-tumor therapies targeting these ICP splice variants, the AS of CD44 creates novel molecular targets, which can be used for novel anti-tumor immunotherapies." (PMID 38736877, 2024). "Studies also show that CD44 is a marker of CSCs and a regulator of tumor self-renewal, initiation, and metastasis." (PMID 39188680, 2024). "Encouraging preclinical results, such as the remarkable tumor inhibition by CD44-targeted NIR-PIT and the efficacy of specific inhibitors in reducing metastatic spread, highlight the potential of these approaches." (PMID 38612911, 2024). "Upon TMZ treatment, Galectin signaling was linked to Lgals9 produced by myeloid cells predicted to interact with Cd44 in tumor cells and Ptprc (Cd45) in ependymal and myeloid cells." (PMID 38566128, 2024). "The possible mechanisms by which CD44 primarily promotes tumor cell proliferation with suppression of tumor cell invasion need to be determined." (PMID 37835592, 2023). "Another important feature is that CD44 has differently spliced isoforms, and this can also explain how CD44+ tumor cells differently mediate biology; e.g., CD44v3 isoform is associated with increased cell migration and invasion." (PMID 38188613, 2023). "A still unsolved question relates to the possible tumor-promoting effects of CD44/hyaluronan engagement and, hence, to the safety of HA-conjugated drugs." (PMID 37958796, 2023). "BCSCs were indeed more prevalent in ER- and TNBC cells, while differentiated tumor cells (ALDH-non-CD44+CD24−/low) were primarily found in Luminal A and HER2amp cells." (PMID 37771376, 2023). "The migratory and invasive activities of cancer stem cells are highly enhanced by the high expression of CD44, promoting local tumor recurrence and metastasis." (PMID 37760811, 2023). "These areas exhibited mild staining for ALDH1 and strong staining for CD44, particularly within the core regions of tumor islands." (PMID 38126564, 2023).